AXL (AXL receptor tyrosine kinase)
Diseases named in the same sentence as AXL in open-access papers (continued):
Sharing a sentence is not in itself a finding about the gene and the disease.
ZIKV infection (continued). "Dysregulation of the neuronal genes, such as RBBP8, ASPM, AXL, TBR2, MCPH1, and CENPF upon ZIKV infection may cause different neurological or brain development related disorders." (PMID 33891593, 2021). "Other mouse models also show that pancreatitis, conjunctivitis, and eye infections caused by ZIKV infection are not related to AXL." (PMID 33954117, 2021). "However, in mice, murine AXL has different effects on ZIKV infection, such as mediating the expression of interleukins and the apoptosis of nerve cells." (PMID 33954117, 2021). "Since we observed only partial suppression of ZIKV infection with AXL blockade, other TAM receptors may also mediate ZIKV entry into fcMSCs." (PMID 32941515, 2020). "Our data clearly demonstrate that AXL is important for ZIKV infection in HBVP." (PMID 32357162, 2020). "According to previous studies, AXL was considered as a candidate entry factor for ZIKV infection." (PMID 32849457, 2020). "Out of the putative ZIKV receptors, AXL is the most studied receptor in regards to ZIKV infection." (PMID 30374352, 2018). "Genetic knockdown of AXL in a glial cell line nearly abolished ZIKV infection." (PMID 29724036, 2018). "Recently, we showed that AXL is also important for ZIKV infection of human Sertoli cells." (PMID 30453621, 2018). "Another controversial molecule in ZIKV infection is the cellular receptor AXL." (PMID 30453684, 2018). "Nevertheless, AXL might have a role in ZIKV infection of glial cells via Gas6 mediated activation of AXL kinase." (PMID 30319635, 2018). "The protein AXL mediates entry into human microglia and astrocytes and modulates innate immune responses, confirming previous studies suggesting this host factor is important for ZIKV infection." (PMID 28645311, 2017). "To define the players that could be involved in ZIKV infection in the placenta, we explored the expression of proteins previously associated with other viral infections and innate immunity, namely CSTB, RAGE, and AXL." (PMID 36429055, 2022). "Interestingly, at mid-neurogenesis, AXL is expressed in a highly reproducible pattern throughout the cortex, with strong expression bordering the lateral ventricle and in the outer subventricular zone, which is consistent with ZIKV infection tropism zone." (PMID 33954117, 2021). "Whilst this might throw into question whether AXL is indeed required for the destructive effects of ZIKV infection, a growing body of data continues to implicate AXL in the assistance of ZIKV viral entry and modulation of the downstream immune response in infected cells." (PMID 33499699, 2021). "However, studies in AXL deficient mice suggest that it is not required for ZIKV infection in these tissues." (PMID 32544190, 2020). "However, cerebral organoids derived from AXL-knockout hPSCs could still be infected efficiently and subsequently displayed microcephaly-related phenotypes, suggesting that AXL is dispensable for ZIKV infection in human neural stem cells." (PMID 30704043, 2019). "Interestingly, it has recently been demonstrated that silencing the AXL gene was unable to inhibit viral entry but rather facilitates the upregulation of type 1 interferon signaling, indicating that AXL promotes ZIKV infection in glial cells by antagonizing type I interferon (IFN) signaling." (PMID 30374352, 2018). "TAM receptors (Tyro, AXL, and MER-TK) have been studied upon ZIKV infection in mice and microglial cells." (PMID 41373653, 2025). "Previous studies have shown that AXL and CD209 are ZIKV receptors, and in skin cells, AXL is much more efficient than CD209, TYRO3, and TIM in promoting ZIKV infection (24, 26, 52, –, 54)." (PMID 39570015, 2024). "To explore the role of these potential host factors in ZIKV infection of hTSCs, STBTS and EVTTS, we compared the expression of AXL, TYRO3, MERTK and TIM-1 in hTSCs, STBTS and EVTTS by qRT-PCR." (PMID 37684223, 2023).
ZIKV infection (continued). "ZIKV infection was abrogated when the engineered MYD1 is added during the viral challenge and up to 12h post-infection, further confirming the importance of AXL for the viral entry." (PMID 36483552, 2022). "A further study reported the role of AXL in antagonizing ZIKV-induced activation of type I interferon (IFN) signaling, which facilitates ZIKV infection in astrocytes, instead of being a ZIKV entry receptor." (PMID 35308394, 2022). "Several studies have shown that AXL is an important negative regulator of type I IFN signaling and facilitate ZIKV infection by antagonizing type I IFN." (PMID 36089062, 2022). "Our findings have shown that Hc-CATH can reverse the negative regulation of AXL on type I IFN response, which seems to be an important antiviral mechanism of Hc-CATH against ZIKV infection." (PMID 36089062, 2022). "After AXL−/− mice are infected with ZIKV, high levels of ZIKV infection are still present in the testes and epididymis, which suggests that AXL is likely dispensable for ZIKV pathogenesis in the male reproductive tract." (PMID 33954117, 2021). "For example, AXL, a member of the TAM receptor family, has been shown to be an attachment factor for ZIKV infection in 293 T cells, keratinocytes, and endothelial cells." (PMID 32544190, 2020). "AXL from the TYRO3, AXL, and MERTK (TAM) family of receptor tyrosine kinases was recently found to support ZIKV infection of human glial cells, neural stem cells, skin fibroblasts, and fetal endothelial cells." (PMID 31824472, 2019). "This affinity for astrocytes is likely due to their high expression of AXL, a putative receptor for ZIKV, which interacts with Gas6 to promote ZIKV infection." (PMID 30572570, 2018). "Inhibition of AXL by synthetic decoy receptor (MYD1) and AXL kinase inhibitor (R428) resulted in the inhibition of ZIKV infection in the glial cells." (PMID 30374352, 2018). "Several entry receptors including the innate immune receptor DC-SIGN, transmembrane protein TIM-1 and TAM receptors (TYRO3, AXL, MER), have been shown to facilitate entry and enhance ZIKV infection." (PMID 30319635, 2018). "However, all the TAM receptors (Tyro-3, AXL, and MER-TK) showed significant (p < 0.05) downregulation in the murine cortical neurons at 72 h post ZIKV infection when compared to their respective uninfected control group of cortical neurons." (PMID 41373653, 2025). "It is possible that an alternative mechanism is at play for ZIKV infection in the absence of AXL, and this mechanism can be the same for AXL-independent infection by DENV." (PMID 40062839, 2025). "However, recent research using gene knockout and overexpression strategies in human trophoblast stem cells and organoids has shown that AXL and TIM-1, another putative ZIKV entry receptor contribute to the high sensitivity of the placenta to ZIKV infection." (PMID 38957469, 2024). "Therefore, AXL and TIM-1 likely work together to enable ZIKV infection at the maternal-fetal interface, but further research is required." (PMID 38957469, 2024). "Despite this, knockout of AXL did not protect human neural progenitor cells and cerebral organoids from ZIKV infection." (PMID 38957469, 2024). "Despite AXL being an important cellular receptor of ZIKV infection, we found no change in AXL expression on monocytes in whole blood or tissues of SIV+ animals following ZIKV challenge." (PMID 39229223, 2024). "The role of AXL and TIM-1 in ZIKV infection of human host cells was also studied in other tissues." (PMID 37684223, 2023). "AXL and TIM-1 played important roles in ZIKV infection of trophoblast cells." (PMID 37684223, 2023). "To examine whether AXL or TIM-1 could endow EVT permissiveness to ZIKV infection, we constructed doxycycline (DOX)-inducible hTSCs overexpressing AXL (TRE_AXL) or TIM-1 (TRE_TIM-1)." (PMID 37684223, 2023). "However, the genetic ablation of AXL using CRISPR-Cas9 in neural precursor cells (NPCs) and cerebral organoids was insufficient in inhibiting ZIKV infection." (PMID 38137537, 2023).
ZIKV infection (continued). "Moreover, the replication of ZIKV RNA was also reduced in AXL-/- and TIM-1-/- hTSCs, indicating the important roles of AXL and TIM-1 in ZIKV infection of hTSCs." (PMID 37684223, 2023). "In conclusion, the role of AXL and TIM-1 differs in ZIKV infection of different cell types." (PMID 37684223, 2023). "Furthermore, we found AXL, a TAM family tyrosine kinase that has been described as a facilitator of ZIKV infection due to attenuation of type I IFN, was found to be absent from neutrophils’ surface." (PMID 35747137, 2022). "On the other hand, AXL can regulate the innate immune response of host cells by negatively regulating interferon (IFN) signaling and the expression of inflammatory factors, thus promoting ZIKV infection." (PMID 36089062, 2022). "Nevertheless, another study described that AXL is not essential for Zika virus infection in NPCs and organoids with genetically excised AXL." (PMID 35847376, 2022). "Genetic elimination of AXL does not protect human neural progenitor cells and cerebral organoids from ZIKV infection." (PMID 36404916, 2022). "As these results indicate, the inhibition of AXL alone does not seem to be enough to ameliorate Zika virus infection during brain tissue development." (PMID 35847376, 2022). "During a ZIKV infection in Sertoli cells, the transcription factor STAT1, an important molecule in the AXL-IFNAR signaling pathway, is activated; promoting the expression of suppressor of cytokine signaling 1 (SOCS1) and the restriction of the interferon response." (PMID 36557673, 2022). "Additionally, AXL and TYRO3 facilitate the ZIKV infection of astrocytes and microglia cells whereas AXL facilitates the infection of neural stem cells, neural crest cells, and mesenchymal stem cells." (PMID 35736984, 2022). "Whilst this scRNA-seq study provided a tantalizing entry mechanism for this devastating virus, it should be noted that a later study found AXL was not required for ZIKV infection of cerebral organoids." (PMID 33499699, 2021). "Collectively, we demonstrated that AXL is not required for ZIKV infection of vaginal or ectocervical epithelial cells." (PMID 35126336, 2021). "Although AXL appears to be not so expressed in mature neurons, this receptor is not the only receptor for ZIKV infection." (PMID 33251156, 2020). "Recent contrasting findings indicated that AXL is not needed in ZIKV infection in human neural progenitor cells, cerebral organoids, and mouse models." (PMID 31824472, 2019). "For instances, inhibiting, downregulating, knocking-down, or ablating AXL, although in some cases they reduce ZIKV infection, they do not completely abolish it, pointing to the use of different cell surface receptors on different cell types." (PMID 30149598, 2018). "While in some cell types it acts as a ZIKV viral entry receptor, it has been demonstrated that AXL does not always perform this role during ZIKV infection." (PMID 30453684, 2018). "Furthermore, blocking both AXL and TIM-1 with antibodies can significantly inhibit ZIKV infection, indicating that both receptors may work together to facilitate viral entry." (PMID 40573410, 2025). "Although AXL is a key receptor of ZIKV infection, we found no change in AXL expression on monocytes in whole blood or tissues of SIV+ animals after ZIKV challenge, suggesting that enhanced ZIKV persistence during SIV infection is not due to increased receptor engagement." (PMID 40103823, 2025). "Importantly, treatment with either JAKi or small interfering RNA (siRNA) targeting the interferon alpha receptor 1 (IFNAR1) did not rescue ZIKV infection in the AXL KO cells in contrast to the results from the astrocytes." (PMID 40062839, 2025). "Re-expressing AXL, but not the kinase-dead mutant, was able to significantly rescue ZIKV infection." (PMID 40062839, 2025). "Nevertheless, ZIKV receptors and co-receptors are still not well characterized, and AXL is just one of the cell surface molecules that could help to mediate ZIKV infection." (PMID 35747137, 2022).
ZIKV infection (continued). "It has been proven that AXL is not required for ZIKV infection in neural progenitor cells (NPCs)." (PMID 35371036, 2022). "Our prior work showed that differential infectivity across a range of neuroblastoma cell lines to ZIKV infection did not correlate with AXL expression, and our transcriptional data here indicate that CD24-low and -high cells do not differ in the levels of AXL expression." (PMID 36016357, 2022). "Because of the differences in species and the complexity of virus replication, the key target receptor for ZIKV infection in mice is not AXL but other molecules such as TIM1, DC-SIGN L-SIGN, or some unknown proteins." (PMID 33954117, 2021). "During ZIKV infection, AXL mediates ZIKV entry indirectly whereby the phosphatidylserine extension on ZIKV lipid membrane binds to Growth arrest-specific 6 (Gas6), one of the ligands for AXL that serves as a bridge for ZIKV and AXL interaction, resulting in clathrin-mediated virus internalization." (PMID 31959174, 2020). "AXL expressed on human glial cells can permit ZIKV binding and entry into the host glial cells and small molecule compounds targeting AXL may be effective in inhibiting ZIKV infection." (PMID 31866959, 2019). "However, recent findings also suggest that AXL is not required in ZIKV infection in mouse models, neural progenitor cells, and cerebral organoids." (PMID 30898036, 2019). "However, the role of AXL, variation in the expression of AXL and TYRO3 in pregnant women and whether TIM-1 is the sole receptor for ZIKV infection of the placenta need further study." (PMID 30319635, 2018). "AXL-mediated infection by ZIKV has been shown in a variety of endothelial cells including human umbilical vein endothelial cells (HUVECs) and could play a role in ZIKV infection of brain endothelial cells, and specifically, i-BECs." (PMID 29759080, 2018). "However, although Axl mRNA is expressed in all major neural cell types in the mouse, recent studies suggest that AXL is not important for ZIKV infection in mice." (PMID 28645311, 2017). "In addition, their ectopic expression did not increase WT ZIKV infection in the AXL KO cells." (PMID 40062839, 2025). "Knockout mice for Axl infected with ZIKV exhibited similar viral loads, clinical manifestations, viral distributions, and survival rates compared to WT mice, suggesting that AXL may not be an indispensable factor for ZIKV infection or that ZIKV infection might involve multiple receptors." (PMID 38137537, 2023). "We identify AXL as the top hit in a CRISPR/Cas9 genome-wide screen in human glioblastoma cells and establish a definitive role of AXL, but not TYRO3 or MerTK, for ZIKV infection." (PMID 40062839, 2025). "AXL expression was not significantly changed on ZIKV cellular targets in whole blood, rectum and PLN in either group post-ZIKV infection." (PMID 40103823, 2025). "Additionally, AXL expression was not significantly changed on ZIKV cellular targets in whole blood, rectum and PLN in either group post-ZIKV infection." (PMID 39229223, 2024). "However, other studies have shown that AXL does not serve as ZIKV receptor in human astrocytes, but rather promotes ZIKV infection through suppression of type I IFN signaling." (PMID 33432092, 2021). "However, evidence supports that AXL is not indispensable for ZIKV entry, and its role in ZIKV infection could be cell type-specific." (PMID 35371036, 2022). "AXL is the main ZIKV candidate receptor, present in several cell types such as keratinocytes, HEK 293T, neuronal stem cells, astrocytes, oligodendrocyte precursor cells, microglia and endothelial cells, but its removal does not protect from ZIKV infection suggesting that others are involved." (PMID 29382068, 2018). "Downregulation of AXL by an AXL inhibitor R428 or an AXL decoy receptor MYD1 significantly reduced but did not abolish the ZIKV infection, suggesting the AXL receptor might be the primary but not the only receptor that is required for ZIKV infection." (PMID 29724036, 2018).
ovarian carcinoma (65 papers, 2008 to 2026). A malignant neoplasm originating from the surface ovarian epithelium. "In this study, we explored the antitumor activity of gilteritinib in AXL-expressing esophageal cancer (EC), ovarian cancer (OC), and gastric cancer (GC), along with the underlying molecular mechanisms." (PMID 40157901, 2025). "The growth arrest-specific protein 6 (GAS6) – AXL tyrosine kinase (AXL) interaction, for example, which are both associated with poor outcome, have already been evaluated in clinical trials in ovarian cancer by inhibiting their interaction." (PMID 39669575, 2024). "AXL is overexpressed in multiple cancer types, including ovarian cancer, causing malignant phenotypes and a poor prognosis." (PMID 32385243, 2020). "Similarly, in patients with ovarian cancer or endometrial cancer, high AXL expression is associated with poor chemoresponse and patients with ccRCC who have high AXL expression shows lower objective response rate to PD-1 inhibition therapy." (PMID 37328828, 2023). "The inclusion of platinum-resistant ovarian cancer as an expansion cohort in the study was based on the literature suggesting that platinum resistance may promote a mesenchymal phenotype, which is associated with elevated AXL expression in tumors." (PMID 41166388, 2025). "In this study, we demonstrated that AXL is extensively N-glycosylated in breast and ovarian cancer cells, existing predominantly as two isoforms corresponding to high-mannose and complex-type glycans." (PMID 42055283, 2026). "Early clinical trials have demonstrated promise in patients with advanced malignancies, including ovarian cancer, indicating its potential as a treatment option for AXL-positive tumors." (PMID 41347223, 2025). "In the last decade, there has been a growing recognition of the important role that AXL and other RTKs play in ovarian cancers and their role in signaling through PI3K/AKT and MEK/ERK signaling pathways." (PMID 40699804, 2025). "Inhibition of AXL has been shown to block tumour formation, metastasis, and reverse drug resistance in several experimental cancer models, including ovarian cancer." (PMID 40696160, 2025). "Silencing AXL or blocking the GAS6-AXL pathway has been shown to prevent regional dissemination of ovarian cancer cells in vivo, demonstrating AXL to be a critical factor in ovarian tumour metastasis." (PMID 40696160, 2025). "Another phase I/II clinical trial (NCT04019288) was designed and was commenced in 2019 to evaluate the safety and clinical benefit of durvalumab plus AVB-S6-500 (an AXL inhibitor) in platinum-resistant ovarian cancer patients." (PMID 38539161, 2024). "AXL was overexpressed in a wide range of cancers including breast, lung and ovarian cancer, and the expression level was directly correlated with poor prognosis of cancer." (PMID 39598377, 2024). "Inhibition of AXL (via bemcentinib or MYD1-72) resensitizes ovarian cancer cells to platinum, ATR inhibitors (ATRis) and PARPis by increasing DNA damage and inducing RS." (PMID 38539161, 2024). "Blocking GAS6/AXL signaling was also reported to increase DNA damage to sensitize ovarian cancer to chemotherapy and PARP inhibition." (PMID 38906855, 2024). "AVB-500, a high-affinity AXL fusion protein, effectively increasing the chemosensitivity of ovarian cancer and endometrial cancer, is currently being tested in a Phase Ib clinical trial against platinum-resistant ovarian cancer." (PMID 37475048, 2023). "In an ovarian cancer model, AXL inhibition results in a DDR response and sensitivity to ATR inhibition, and the AXL binding partner SAM68 shows DNA damage phenotypes upon loss, similar to AXL inhibition." (PMID 37349576, 2023). "PRKRA was also found to promote chemoresistance in ovarian cancer by downregulating miRNA-515-3p and upregulating AXL." (PMID 37484321, 2023).